IL6 (interleukin 6)
Diseases named in the same sentence as IL6 in open-access papers (continued):
Sharing a sentence is not in itself a finding about the gene and the disease.
tumor (continued). "Blocking key signaling pathways (e.g., TGF-β, IL-6, CXCL12) can disrupt the tumor-supporting effects of CAFs." (PMID 41590379, 2026). "This is accompanied by significant reductions in IL-6, MIP-2, and VEGF levels, reprogramming the tumor microenvironment to support CD8 T-cell infiltration." (PMID 40812468, 2026). "Thermal triggers tumor cell expression of HSP70/90, boosts antigen presentation efficiency, and stimulates IL‐6 and TNF‐α secretion to activate innate immunity and enhance immune recognition of tumor cells." (PMID 41298282, 2026). "Immune cell infiltration, such as macrophages, releases proinflammatory cytokines (IL-6, IL-17, TNF-α), which enhance tumor proliferation, survival, and invasion." (PMID 41438576, 2026). "Treatment of mesenchymal stromal cells (MSCs) isolated from lung cancer patients led to a significant reduction in the production of IL-6 and chemokines like CCL2, and CCL3 that play key roles in tumour progression and immune modulation." (PMID 40943351, 2025). "Tumor-secreted factors such as PTH-related protein (PTHrP), interleukin-6 (IL-6), IL-11, and prostaglandin E2 stimulate osteoblasts and stromal cells to increase the expression of RANKL." (PMID 40941035, 2025). "Cells undergoing EMT secrete cytokines and growth factors, such as TGF-β, IL-6, and VEGF, which support angiogenesis, immunosuppression, and the formation of protective niches within the tumor." (PMID 40362280, 2025). "M1-type macrophages kill tumor cells by releasing reactive oxygen species (ROS), nitric oxide (NO), and pro-inflammatory cytokines, TNF-α, IL-6, IFN-γ, over days and through antibody-dependent cell-mediated cytotoxicity (ADCC) within hours." (PMID 40260236, 2025). "Pro-inflammatory cytokines, such as IL-6, TNFα, IL-1β, and IFNγ, enhance the activation of key signaling pathways like NF-κB and STAT3, which drive tumor progression." (PMID 40943532, 2025). "For instance, MMP-7 and MMP-9 have been shown to influence the availability of cytokines like interleukin-6 (IL-6) and tumor necrosis factor-alpha (TNF-α), modulating inflammatory signaling and dampening immune cell responses in the tumor microenvironment." (PMID 40265458, 2025). "For example, macrophages in SCLC secrete interleukin-6 (IL-6), which activates the signal transducer and activator of transcription 3 (STAT3) signaling pathway to promote tumor growth." (PMID 41194225, 2025). "CAFs remodel the ECM and enhance tumor cell invasiveness by secreting cytokines (e.g., TGF-β, IL-6) and chemokines (e.g., CCL2, CXCL12), promoting angiogenesis and inducing EMT." (PMID 41430036, 2025). "By disrupting the IL-6/STAT3 interplay, this process further hinders the signaling pathway, thereby mitigating the stemness properties of tumor cells." (PMID 40230836, 2025). "Experimental studies suggest that blocking IL-6 can enhance CD8+ T cell accumulation and increase tumor cell sensitivity to anti-PD-1 treatment." (PMID 41476977, 2025). "Tumor-derived factors such as VEGF, IL-6, and IL-10 accumulate MDSCs which in turn secrete more VEGF via STAT3 signaling, thus augments angiogenesis." (PMID 40165901, 2025). "Emerging strategies aim to reprogram the TME by targeting SASP components, such as IL6, IL1β, and TNF-α, which promote tumor progression." (PMID 40781676, 2025). "HIF-1α activation in hypoxic regions induces IL-6 secretion, which in turn stimulates FPN expression in macrophages, enhancing iron export and availability to tumor cells." (PMID 40861444, 2025). "These M2 macrophages support tumor growth through immunosuppressive actions, angiogenesis, and extracellular matrix remodeling, while also secreting factors like IL-6 and TNF-α that reinforce CSC stemness and contribute to tumor progression and metastasis." (PMID 40330466, 2025). "We examined the activity of EEP PL and quercetin on the production of IL-6, VEGF, PDGF-BB, IP-10, MCP-1 and IL-9 by the CCF-STTG1 cell line present in the tumour microenvironment of CNS." (PMID 40733274, 2025).
tumor (continued). "IL-6 and IL-1β activate STAT3/NF-κB pathways in tumor cells, enhancing proliferation, invasion, and stemness." (PMID 41007766, 2025). "A significant article summarizes the mechanisms through which pro-inflammatory cytokines, including the IL-1 family, IL-6, and TNF-α, exert pro-tumorigenic or tumor-suppressive effects during tumorigenesis." (PMID 39875357, 2025). "IL-6, TNF-α, and CXCL8 are three key pro-inflammatory cytokines extensively involved in remodeling the TME, thereby promoting tumor cell proliferation, metastasis, and immune evasion." (PMID 41376630, 2025). "EGFR activation has been shown to interact with inflammatory pathways such as NF-κB and IL-6/STAT3, leading to enhanced tumor proliferation, angiogenesis, and an immunosuppressive microenvironment." (PMID 41268168, 2025). "Targeting IL-6/JAK/STAT-3 pathway is another therapeutic approach directed against the TME, as IL-6 regulates many tumor-promoting functions." (PMID 40940764, 2025). "In the urethane-induced lung carcinogenic model, emodin reduces hypercoagulation and tumor lesions, accompanied by a decrease in N2 neutrophils and modulated cytokine profiles (IFN-γ, IL-12 up; IL-6, TNF-α, TGF-β1 down)." (PMID 40490812, 2025). "IHC analysis of TNF‐α and IL‐6 in tumour tissues showed that GlyGCC (+) EVs increased TNF‐α and IL‐6 expression compared to control EV treatment." (PMID 40326665, 2025). "Whereas, iCAFs were located distantly from the tumor cells and characterized by low α-SMA expression and secretion of inflammatory mediators including IL6, C-X-C motif chemokine ligand 1 (CXCL1), LIF, IL11, and CXCL2." (PMID 40296919, 2025). "Studies have shown that HuR promotes chronic inflammation by stabilizing TNF-α and IL-6 mRNAs and enhancing their expression within the tumor microenvironment (TME), thereby suppressing anti-tumor immune responses." (PMID 41200195, 2025). "Inflammatory cytokines (e.g., IL-6, TNF-α) in the tumor microenvironment stimulate PCT production, rapidly elevating its blood concentration." (PMID 40400626, 2025). "Additional research has indicated that CAFs in HCC enhance tumor-initiating cell characteristics and therapeutic resistance by releasing HGF and IL-6, which activate the FRA1 and Notch signaling pathways, respectively." (PMID 40755769, 2025). "Resveratrol has been shown to downregulate the production of pro-inflammatory cytokines, such as TNF-α, IL-6, and IL-1β, thereby disrupting the signals promoting inflammation within the TIME and hindering tumor growth and progression." (PMID 40940890, 2025). "A recent study found that, in mice model, a high fat diet elevated IL-6 secretion by prostate macrophages, which triggered STAT3-driven growth of myeloid-derived suppressor cells and fostered a tumor-promoting." (PMID 39891849, 2025). "Results showed that all VIF values were below the threshold of 10, with specific values as follows: AFP (VIF = 3.21), CD147 (VIF = 2.89), IL-6 (VIF = 3.57), capsule integrity (VIF = 1.82), tumor size (VIF = 2.11), and CAR (VIF = 2.98)." (PMID 40919145, 2025). "In vivo, a significant reduction (~89%) in tumor burden and favorable modulation of inflammation, characterized by a decrease in pro‐inflammatory cytokines (TNF‐α, IFN‐γ, IL‐6, VEGF) and an increase in anti‐inflammatory IL‐10 was observed." (PMID 40908716, 2025). "TUBA1B expression also positively correlated with immune-related pathways like interferon-alpha/gamma response, IL-2/STAT5 signaling, and IL6/JAK/STAT3 signaling, indicating TUBA1B’s significant role in the tumor immune microenvironment (TIME)." (PMID 39968182, 2025). "For instance, CAFs secrete factors like IL-6, IL-33, and TGF-β, which activate signaling pathways in tumor cells, promoting tumor progression." (PMID 41031085, 2025). "Adiponectin increased tumor promoting IRG1 expression in M0 macrophages, as well as IL6, IL8, and NFKB expression in M0 and M2-like macrophages." (PMID 40552282, 2025).
tumor (continued). "CD8, IL-6, and PD-L1 expression in ESCC tissue microarrays were measured using immunohistochemistry, and then the tumor microenvironment was classified." (PMID 40433391, 2025). "IL-6 and VEGF promote angiogenesis and tumor growth, while IL-4, MCP-1, and other cytokines create an immunosuppressive environment." (PMID 40264780, 2025). "Upon binding to the IL‐6 receptor (IL‐6R) on cell membranes, IL‐6 forms a complex with gp130 or IL‐6Rβ, triggering STAT3 activation and promoting tumor development." (PMID 40166646, 2025). "Numerous cytokines and chemokines such as IL-6, IL-1β, G-CSF, M-CSF, GM-CSF, macrophage migration inhibitory factor (MIF), and TGF-1 were present in the TME which attract MDSCs accumulation at tumor sites." (PMID 40141437, 2025). "Another research discovered that hypoxia-induced MIF causes deregulation of lipid metabolism in Hep2 laryngocarcinoma via the IL-6/JAK-STAT (signal transducer and activator of transcription) axis leading to tumor progression." (PMID 41159021, 2025). "Iron chelation and FPN induction have been shown to reduce IL6 mRNA and deactivate the STAT3 pathway, lowering intracellular iron levels and inhibiting OC tumor cell proliferation and metastasis." (PMID 40427188, 2025). "Pro-inflammatory cytokines such as IL-1β, IL-6, and TNF-α not only drive tumor progression and invasion but also contribute to chemotherapy resistance, underscoring their relevance as both biomarkers and therapeutic targets." (PMID 41155372, 2025). "Cytokines including CCL-2, IL-6, IL-8, IL-10, IL-13, and TNF-α show tumor-specific secretion profiles, with experimental evidence demonstrating TIC-derived cytokines mediate immune evasion through recruitment and activation of MDSCs and TAMs." (PMID 40777043, 2025). "Inflammatory cytokines such as IL-6 and TNF-α upregulate HIF-1α and KRAS signaling, further enhancing tumor aggressiveness and resistance to therapy." (PMID 40342817, 2025). "The tumor cells produce several factors, such as VEGF, IL-6, and PGE2, to inhibit FLT3L activity and prevent cDC1, moDC, and pre-DC maturation, differentiation, and survival in the TME, causing an immunosuppressive environment for tumor progression." (PMID 41176596, 2025). "Various tumor-derived factors induce differentiation of MDSCs in vitro, including PGE2, IL-6, IL-10, IL-1β, TGF-β, stem cell factor (SCF), and proangiogenic VEGF." (PMID 40940764, 2025). "Inflammatory cytokines in TME, such as IFN-ꝩ, IL-1β, IL-6, and TNF, further favorize cancer immune escape by augmenting PD-L1/PD-L2 expression on tumor cells including TNBC." (PMID 40940764, 2025). "In head and neck squamous cell carcinomas, inhibiting the triple combination of IL-6, IL-8, and CXCL-1 has been shown to be highly effective in reducing tumour cell activity." (PMID 41009413, 2025). "Tumor-produced PGE2 (via COX-1/2) and IL-6 can likewise inhibit DCs differentiation through STAT3 signaling, skewing DCs to produce more IL-10 but less IL-12, thereby promoting regulatory or TH2 responses over TH1 cytotoxic immunity." (PMID 41488634, 2025). "We examined the activity of ethanolic extract of Brazilian green propolis on the production of cytokines IL-6, IFN-γ, VEGF, and PDGF-BB by astrocytes present in the tumor CNS microenvironment." (PMID 40143164, 2025). "TAMs promote tumor progression via key signaling pathways, including TGF-β/BMP, TNF-α/Wnt, IL-6/STAT3/IRF4, and Wnt/β-catenin, each regulating cell motility, survival, and immune suppression." (PMID 41459539, 2025). "CAFs recruit MDSCs from the bone marrow to the tumor site by secreting cytokines such as CCL2, CSF-1 and IL-6." (PMID 40934009, 2025). "Our study observed high IL-6 expression in ESCC, which correlated closely with immune cells and PD-L1 expression, contributing to a significantly suppressed tumor immune microenvironment." (PMID 40433391, 2025).
tumor (continued). "Here, we identified CRC‐specific RNA modifications in EVs that promote tumour growth by enhancing tumour necrosis factor (TNF)‐α and interleukin (IL)‐6 secretion by macrophages." (PMID 40326665, 2025). "Molecular analyses supported these findings, showing significant downregulation of tumor-promoting genes, including VEGF, MMP-9, and IL-6, as well as upregulation of the anti-inflammatory cytokine IL-10." (PMID 40808199, 2025). "These concordant findings strengthen the evidence for IL-6 upregulation in CRC and underscore its potential involvement in tumor-related inflammation." (PMID 41007818, 2025). "CD19/CD22 dual-target CAR T is more likely to target tumor cells with high CD22 expression, reduce overkill of normal B-cells, and thus reduce the total amount of systemic inflammatory factors (such as IL-6, IFN-γ) released." (PMID 40433368, 2025). "These reprogrammed astrocytes secrete IL-6 and IL-1β, activating JAK2/STAT3 signaling in tumor cells and enabling dynamic switching between dormancy and proliferation within the CNS niche." (PMID 41562063, 2025). "Of the 12 chemokines compared, IL-6, Angiopoietin-2, IL-8, and CEACAM-1 were significantly higher in the tumor group (IL-6: p = 0.02, Angiopoietin-2: p = 0.007, IL-8: p = 0.003, CEACAM-1: p = 0.001)." (PMID 39652104, 2025). "For example, IL-6 in the TME activates JAK/STAT, promoting tumor growth, while pathways like MEK/ERK maintain tumor integrity." (PMID 39996827, 2025). "IL-6 exerts its effects through the activation of several oncogenic pathways, including JAK/STAT3, PI3K/Akt, and MAPK, which promote tumor cell proliferation, inhibit apoptosis, and enhance metastatic potential." (PMID 41007818, 2025). "Conversely, genetic or pharmacological inhibition of IL-6/IL-6 receptor signaling upregulated MAO-A expression and suppressed these aggressive tumor aspects." (PMID 39714760, 2025). "For instance, IL-6 has been shown to activate NLRP3 via the JAK2/STAT3/SOX4 axis, effectively connecting inflammatory cytokine signaling with inflammasome-mediated tumor enhancement." (PMID 41560727, 2025). "In NSCLC, circNOX4 promotes the secretion of interleukin 6 (IL‐6) to establish an inflammatory niche via the miR‐329‐5p/FAP axis, enhancing tumor progression." (PMID 39901896, 2025). "Growth factors and cytokines (IL-6, IL-7, IL-10, GM-CSF, VEGF, TGF-β) are produced by the surrounding stroma and also by tumor cells, and induce, by coupling to their cell membrane receptors, JAK-STAT3 activation." (PMID 41463071, 2025). "The IL-6/STAT3 signaling pathway is often constitutively triggered in TNBC, hence promoting tumor development and dismal prognosis." (PMID 40868199, 2025). "CAF-Exos are enriched in stromal-modulating proteins like transforming growth factor-beta (TGF-β), Interleukin-6 (IL-6), and Matrix metalloproteinases (MMPs), promoting fibrosis, ECM remodeling, and an immune-excluded tumor phenotype." (PMID 41439998, 2025). "Cytokines such as IL-6 and IL-8, prevalent in the SASP, can promote cancer cell proliferation, motility, and angiogenesis, hence aiding tumor dissemination." (PMID 40507795, 2025). "Fungi induce the secretion of pro-inflammatory cytokines, including IL-17, IL-6, and TNF-α, which activate immune-suppressive mechanisms that, paradoxically, support tumor survival and progression." (PMID 40557321, 2025). "EndMT in the formation of CAFs is primarily driven by key tumor‐derived factors, particularly TGF‐β and IL‐6." (PMID 40656546, 2025). "Elevated IL6 levels in the TME can disrupt the balance between CD8+ T cells and Tregs, promoting tumor growth and reducing the effectiveness of chemotherapy." (PMID 40427188, 2025). "In HER2-positive BC, IL6 induces the production and maintenance of BC stem cells through the NF-κB p65 and STAT3 signal pathways, promoting tumor progression." (PMID 40841364, 2025).
tumor (continued). "IL-6 activates the JAK/STAT3 signaling in tumor cells and tumor-infiltrating immune cells, participating in the construction of an adverse TIME, potentially facilitating AST." (PMID 40568576, 2025). "Second, the anti-tumor effects of CCNB1/CDK1 inhibition extend beyond PD-L1 regulation, including modulation of the IL-6-JAK-STAT3 axis and TGF-β signaling." (PMID 40430484, 2025). "Tumor-related inflammatory cytokines, such as TNF-α and IL-6, contribute to skeletal muscle atrophy by promoting protein degradation through activation of the NF-κB and UPS pathways." (PMID 40104495, 2025). "As noted in previous studies of the TME, IL-6 trans-signaling promotes the interaction between GP130, soluble IL-6 receptor (sIL-6R), and IL-6, driving JAK-STAT-dependent tumor cell migration." (PMID 40384867, 2025). "Their functional maturation is promoted by cytokines such as IL4, IL6, IL13, and TNF, while mobilization into the tumor niche is orchestrated by chemoattractants including IL8, CCL2, and CXCL12." (PMID 41155172, 2025). "CAFs secrete factors like TGF-β, IL-6, VEGF, and PDGF, which drive tumor progression by enhancing angiogenesis and creating a pro-tumorigenic microenvironment that supports tumor cell survival and migration." (PMID 40038745, 2025). "Compared to the blank group, the high-fat diet-fed model group exhibited increased interleukin (IL)-6 and tumor necrosis factor (TNF)-α levels, showing enhanced inflammation and tumor development." (PMID 40869014, 2025). "It regulates the expression of proinflammatory cytokines, such as TNF-α, interleukins (IL-1, IL-2, IL-6, IL-8, IL-12), and the chemokine cyclooxygenase-2 (COX-2), molecules involved in tumor initiation and progression." (PMID 40572668, 2025). "The activation of TLR2/TLR4 by HSPs causes the activation of HSF1 signaling followed by NF-kB signaling in DCs, resulting in the release of cytokines (IL-1, IL-6, and TNF) and the release of tumor antigens, which can be processed by APCs." (PMID 41375025, 2025). "A cascade of pro-tumorigenic factors, including IL6, VEGFA, IL11, PDGFA, and CXCL12, further amplify the formation of complex microenvironments that support tumor cell colonization and proliferation, exacerbating the progression of CRLM." (PMID 39979806, 2025). "CAFs in the TME secret multiple tumor-promoting cytokines, such as IL-6 and TGF-β to support tumor growth." (PMID 40248695, 2025). "This HIF-1α/IL-6/FPN pathway reshapes the iron distribution within the TME, favoring tumor cell proliferation and impairing anti-tumor immune responses." (PMID 40861444, 2025). "Our previous studies demonstrated a significant increase in TNF-α, IL-6, IL-18, IL-1β, and INF-γ in the skeletal muscle of tumor-bearing animals, which normalized after treatment with withaferin A (WFA)." (PMID 39996717, 2025). "MSC2: Secretion of CCL5, TGF‐β, IL‐6, VEGF, IL‐8, IL‐10, MMPs (Induction of angiogenesis, metastasis, enhanced tumor stemness, immunosuppression, differentiation into CAF)." (PMID 40150879, 2025). "Tumor EVs can propagate systemic inflammation (elevated CRP, IL-6, etc.)by ferrying inflammatory mediators that feed into the muscle and fat catabolism." (PMID 40869331, 2025). "In breast cancer organoid models and tumor-associated macrophage cocultures, UA suppressed proinflammatory cytokines, including IL-6 and TNF-α, creating a tumor microenvironment with reduced inflammation." (PMID 40568370, 2025). "Specifically, IL-6 is a crucial component of the TME and can be produced by tumour cells themselves or possibly by CAFs and TAMs." (PMID 41009413, 2025). "They express CD86 and secrete IL-6, TGF-α, and CCL1, contributing to immune escape mechanisms and promoting tumor growth." (PMID 40055311, 2025). "Several cytokines such as GM-CSF, IL-6, IFN-γ, and IL-1β have been identified as inducers of tumor MDSC." (PMID 41360769, 2025).